MPO (myeloperoxidase)
Diseases named in the same sentence as MPO in open-access papers (continued):
Sharing a sentence is not in itself a finding about the gene and the disease.
myocardial infarction (continued). "With respect to myocardial infarction, the role of Annexin A1 in neutrophil infiltration and MPO activity were explored in rat." (PMID 34943928, 2021). "Further, gavage administration of the MPO inhibitor PF-1355 for 7 days also inhibits the increase in MPO activity in the myocardial infarction area of mice, reduces the number of inflammatory cells, and slows down the expansion of the left ventricle." (PMID 33680285, 2021). "In fact, infusion of recombinant ANXA1 decreases myocardial infarct size and the treatment with Ac2-26 reduces both infarct size, myeloperoxidase (MPO) and IL-1β levels." (PMID 33804219, 2021). "Elevated levels of MPO activity in the plasma are observed in myocardial infarction and in ACS, and high MPO concentrations are associated with major adverse cardiovascular events in patients with CAD." (PMID 34359938, 2021). "The MPO test is widely used to measure the accumulation of polymorphonuclear leukocytes (PMNL) during myocardial infarction, lung infections, and skin and intestinal inflammation." (PMID 32742649, 2020). "PNS pretreatment before myocardial ischemia can reduce MPO release and improve cardiac function as well as reduce myocardial infarct size during reperfusion." (PMID 33134375, 2020). "The combined values of MPO, CK-MB, and TnI have shown a more accurate diagnosis of myocardial infarction." (PMID 33238444, 2020). "MPO-derived oxidants increase myocardial collagen deposition, play a major role in left ventricular remodeling after myocardial infarction (MI), and increase vulnerability to atrial fibrillation." (PMID 33287422, 2020). "This study tested the efficacy of the MPO inhibitor and antioxidant 4-MetT in an experimental model of myocardial infarction." (PMID 33081101, 2020). "In acute myocardial infarction, leucocytes release myeloperoxidase (MPO), resulting in the generation of oxidizing species." (PMID 33344515, 2020). "Research on myocardial infarction searched C-reactive protein, myoglobin, myeloperoxidase, creatine phosphokinase, creatin kinase MB, cardiac troponin T and cathepsin-L, all reporting statistically significant result." (PMID 32040469, 2020). "Surprisingly, the post-surgery values of MPO-DNA complexes in Group 2 results higher than those observed in patients with history of acute myocardial infarction or patients with severe coronary atherosclerosis (p < 0.001)." (PMID 31604985, 2019). "As far as myocardial infarction/ischemia models go, broad-spectrum detrimental roles of MPO have been confirmed both in early and late phases of infarct progression." (PMID 31416120, 2019). "A study on mouse model of acute myocardial infarction showed that IL-37 inhibited the expression of myeloperoxidase (MPO) and NF-κB signaling pathway." (PMID 29805973, 2018). "Increased detection of pro-MPO in plasma from patients with myocardial infarction (MI) compared to healthy controls." (PMID 29590135, 2018). "The MPO-specific peptide was detected in 42% of myocardial infarction samples (n = 5/12) and 22% of control samples (n = 2/9)." (PMID 29590135, 2018). "Using this method, the pro-MPO-specific was detected in 25% of plasma samples from patients with myocardial infarction (n = 3/12), but only in 11% of samples from control subjects (n = 1/9)." (PMID 29590135, 2018). "Here, we demonstrate that pro-MPO is elevated in patients with myocardial infarction indicating its prognostic potential that warrants further study." (PMID 29590135, 2018). "Clinically, myeloperoxidase activity has been used to predict inflammation and oxidative stress in renal failure, myocardial infarction, inflammatory vascular disease, and so on." (PMID 29483924, 2018). "We then used anti-MPO-Sepharose to purify immune-reactive MPO from plasma from patients with myocardial infarction and from healthy controls." (PMID 29590135, 2018). "Studies have shown that MPO levels are a predictor of death after chest pain and acute myocardial infarction." (PMID 28704420, 2017).
myocardial infarction (continued). "Myoglobin (Mgb), Netrin 1, Myeloperoxidase (MPO), and cholesterol are important biomarkers of cardiovascular disease and myocardial infarction." (PMID 28825646, 2017). "Studies performed in patients with myocardial infarction showed that plasma MPO levels are related to mortality as seen in our study." (PMID 28916973, 2017). "MPO activity is widely used to indicate the infiltration and activation of neutrophils in myocardial infarction." (PMID 26265982, 2015). "It is well known, that hs-cTnT is superior to MPO for rapid and accurate diagnosis of acute myocardial infarction among patients presenting with chest pain at the emergency department." (PMID 24892556, 2014). "High concentrations of salivary CRP, myoglobin and MPO, for example appear after myocardial infarction." (PMID 24915044, 2014). "The results demonstrated that compared to MI/R, etanercept reduced myocardial infarction area, myocardial myeloperoxidase (MPO) levels, serum creatinine kinase (CK) and lactate dehydrogenase (LDH) levels, and both serum and myocardial TNF-α production." (PMID 25260027, 2014). "The MPO activity of the resultant samples was assessed by ADHP and validated against samples from MPO-knockout mice in murine disease models of multiple sclerosis, steatohepatitis, and myocardial infarction." (PMID 23861842, 2013). "In a murine model of acute myocardial infarction, the myeloperoxidase/HOCl system was found to be a major source of acrolein." (PMID 23840401, 2013). "After 6 months, leukocyte counts and MPO concentrations were still increased in patients with acute myocardial infarction when compared to controls." (PMID 21188207, 2010). "Elevated MPO plasma levels in patients with unstable angina and acute myocardial infarction have been shown." (PMID 19690642, 2007). "Interestingly MPO was enriched in the proteome of cultured cells, reflecting reports of elevated MPO expression in immature CD10− neutrophils circulating in myocardial infarction patients." (PMID 38822352, 2024). "Our findings suggest that MPO may play a role in the neovascularization following myocardial infarction." (PMID 38322992, 2024). "A prominent example would be an acute coronary event leading to myocardial infarction, in which case the plasma concentration of MPO may be about 10 times as high as the values measured in our study." (PMID 38137627, 2023). "In this study, we aimed to demonstrate that 18F-MAPP can enter cells to detect not only extracellular MPO activity but also intracellular MPO activity to noninvasively track the therapeutic response of the specific MPO inhibitor PF-2999 in living animals induced with myocardial infarction." (PMID 36982778, 2023). "Similarly, another study showed that RESV intake significantly reduced myocardial infarction areas together with myeloperoxidase (MPO) and TFN-α levels in the myocardium." (PMID 35761875, 2022). "Experimental studies using MPO knockout mice or an oral MPO inhibitor showed significant less left ventricle dilation and improved left ventricular function in models of myocardial infarction, evidencing a pathophysiological role of MPO in the development of CHF." (PMID 34707513, 2021). "Myocardial infarction induced with isoproterenol administration resulted in a significant (P < 0.001 vs control) increase in neutrophil infiltration into the myocardium, as evaluated by an increase in MPO activity in heart tissue." (PMID 32211137, 2020). "Examples of diseases that can reliably be diagnosed through salivary analysis are pancreatic (miR-3679-5p and miR-940), lung (cytokines IL1RN, IL1B, CXCL10), and breast cancers (phenylalanine, tryptophan), as well as myocardial infarction (C-reactive protein, myoglobin, and myeloperoxidase)." (PMID 32019170, 2020).
myocardial infarction (continued). "To this end, animals lacking MPO are also protected from cardiac dysfunction, and we have previously demonstrated in a mouse myocardial infarct model that inhibiting MPO activation with a similar MPO inhibitor ameliorated cardiac inflammation and scar formation, thus improving cardiac function." (PMID 30889221, 2019). "Myeloperoxidase (MPO) is a highly abundant protein within the neutrophil that is associated with lipoprotein oxidation, and increased plasma MPO levels are correlated with poor prognosis after myocardial infarct." (PMID 30889221, 2019). "Furthermore, we found that pro-MPO was more frequently detected in plasma from patients with myocardial infarction compared to plasma from control donors." (PMID 29590135, 2018). "Indeed, it has already been shown that plasma MPO levels were an independent predictor of myocardial infarction at two years in patients with AMI." (PMID 28704420, 2017). "Cardiac Tn measured by automated standard assays is superior to all other available biomarkers in clinical practice, including myoglobin, the MB fraction of creatine kinase, myeloperoxidase, and heart fatty acid-binding protein, for the diagnosis of acute myocardial infarction." (PMID 22262955, 2012). "We have studied neutrophil MPO content and its relation to platelet and monocyte activation in patients with segment T elevation myocardial infarction (STEMI), with non elevation myocardial infarction (NSTEMI) and with unstable angina, sampled before any therapeutic intervention." (PMID 22761804, 2012). "In fact, surgeons have demonstrated that high iodide levels reduce infarct size in myocardial infarct subjects with blockage of the descending left anterior artery (STEMI) undergoing primary percutaneous coronary intervention which is likely due to iodo-lipid formation after iodide oxidation by MPO." (PMID 40429993, 2025). "While systemic MPO levels have been associated with poor prognosis in acute CAD patients, studies have shown that elevated systemic MPO levels are linked to increased cardiovascular events, such as myocardial infarction, heart failure, and mortality, in patients with acute CAD." (PMID 38383869, 2024). "Myeloperoxidase (MPO): myeloid-lineage-restricted enzyme with bactericidal properties, found in the azurophilic granules of neutrophils, involved in the neutrophil extracellular traps (NETs) that are implicated in myocardial infarction and in serious cardiovascular events." (PMID 38397436, 2024). "Myeloperoxidase (MPO) is a highly oxidative, pro-inflammatory enzyme involved in post-myocardial infarction (MI) injury and is a potential therapeutic target." (PMID 36982778, 2023). "While myeloperoxidase (MPO) serves as an indicator of both neutrophil and innate-immune-system function, the potential suppression of the innate immune system in patients with acute myocardial infarction (AMI)-induced depression might be evidenced by a decrease in MPO serum levels." (PMID 36358455, 2022). "In patients with acute myocardial infarction (MI), treatment with high-dose O3-FA was associated with a reduction of adverse left ventricular remodeling, noninfarct myocardial fibrosis (ST2), and serum biomarkers of systemic and vascular inflammation (MPO, Lp-PLA2)." (PMID 34453204, 2022). "Furthermore, in patients who are diagnosed with acute myocardial infarction, the MPO level is higher than patients with angina pectoris or stable CAD; meanwhile, there is a significant association between MPO concentration and angiographically detected coronary artery stenosis." (PMID 34422136, 2021). "Plasma MPO concentration was reported to be higher in myocardial infarction (MI) patients (55 ng/mL) as compared to control subjects (39 mg/mL)." (PMID 29669993, 2018).
myocardial infarction (continued). "In prospective studies, high MPO levels were able to predict increased risk of developing CAD in healthy individuals and cardiovascular events in patients presenting to emergency with chest pain and increased risk of myocardial infarction and death in patients with acute coronary syndrome." (PMID 25821554, 2015). "Similarly, Baldus and colleagues evaluated 1090 patients with acute coronary syndromes enrolled in the CAPTURE trial and found that MPO serum levels were predictive of subsequent death and myocardial infarction at 6 months (adjusted hazards ratio 2.25 between patients with high vs. low MPO)." (PMID 23675127, 2009). "In contrast, periodontitis and its relation to coronary artery study (PAROKRANK) found elevated clinical signs of periodontal inflammation and myeloperoxidase and MMP-8 biomarkers in non-myocardial infarction patients." (PMID 38433948, 2024). "MPO and MMP-9 are related to such processes as inflammation, tissue damage, and tissue remodelling in individuals with myocardial infarction." (PMID 37569455, 2023). "Our study proved that there was a positive correlation between MPO and hs-CRP, leukocyte count, neutrophils, and fibrinogen, reflecting the aggravation of inflammatory state during myocardial infarction." (PMID 35419382, 2022). "Myeloperoxidase (MPO) and trimethylamine N-oxide (TMAO) are novel biomarkers of different pathophysiological processes of acute myocardial infarction (AMI)." (PMID 34650427, 2021). "In the current study, we evaluated leukocyte counts and levels of CRP, fibrinogen, MPO, and PAPP-A in patients with stable (SAP) and unstable angina pectoris (UAP), acute myocardial infarction (AMI), and healthy controls (CON)." (PMID 21188207, 2010). "Leukocyte counts and concentrations of fibrinogen, CRP, MPO, and PAPP-A were significantly increased in patients with acute myocardial infarction." (PMID 21188207, 2010). "We evaluated leukocyte counts and levels of CRP, fibrinogen, MPO, and PAPP-A in patients with stable and unstable angina pectoris, acute myocardial infarction, and healthy controls." (PMID 21188207, 2010). "Diabetic patients in this post-myocardial infarction cohort with UCP2 -866 AA/GA genotype have poorer survival and higher myeloperoxidase levels than their GG counterparts." (PMID 19527523, 2009). "MPO inhibitors (AZM198) can stabilize plaques, and serum MPO-DNA complexes can serve as biomarkers for predicting adverse left ventricular remodeling post-PCI in myocardial infarction patients." (PMID 39301029, 2024). "Pharmacological inhibition or congenital absence of MPO decreased post-ischemic fibrosis, reduced left ventricular dilation, and improved left ventricular function in animal models of myocardial infarction." (PMID 36982778, 2023). "We have reported a myeloperoxidase-activatable PET probe (18F-MAPP) that not only detects MPO activity with high sensitivity and specificity but is also capable of monitoring damaging inflammation in mouse models of paw inflammation and myocardial infarction." (PMID 36982778, 2023). "In the present study, high levels of NO and MPO were noticed in the ISO group and the pretreatment of animals with A. pruinosum before the induction of myocardial infarction significantly inhibited cardiac hypertrophy and prevented the rise in cardiac NO and MPO." (PMID 35186101, 2022). "Myeloperoxidase and troponin T assay is a usefuldiagnostic test that can be performed to rule out myocardial infarction in patients with chest pain." (PMID 35815198, 2022). "In some studies, neutrophil-specific MPO and PAD4 ablation or inhibition could improve the disease progression of HF, myocardial infarction, and atrial fibrillation, which all illustrate the fact that NETosis is a pathogenic factor of HF." (PMID 33680285, 2021). "Furthermore, we investigated whether pro-MPO was elevated in patients with myocardial infarction (MI)." (PMID 29590135, 2018).
myocardial infarction (continued). "The objective of this study was to investigate the levels and associations of salivary MMP-8, -9, MPO and tissue inhibitors of metalloproteinase (TIMP)-1 in myocardial infarction (MI) patients and controls with or without periodontitis." (PMID 26132583, 2015). "A functional polymorphism in the MPO promoter gene, which leads to a twofold reduction in MPO expression, is associated with a lower risk for angiographic evidence of CAD, nonfatal myocardial infarction and cardiac death." (PMID 22014237, 2011). "The establishment of these stable complexes may lead to attenuation of MPO activity, which could subsequently lead to a reduction in oxidative stress and inflammation, which are major contributors to myocardial infarction progression and post-MI cognitive deficits." (PMID 39204198, 2024). "To ask whether MPO similarly to TGFβ impacts neovascularization, we performed in vivo experiment, in which number of CD31+ cells, marking capillary ECs, were compared in MPO−/− and MPO+/+ mice after 8 weeks post myocardial infarction." (PMID 38322992, 2024). "Similarly, the CAPTURE trial, which involved 547 patients with resting recurrent chest pain, observed that MPO serum levels of >350 ng/ml were highly predictive of nonfatal acute myocardial infarction within 72 hours." (PMID 34422136, 2021). "A case-control study including 874 angiographically proven CAD patients has shown an advanced MPO level in CAD patients and elevated MPO level in the progress of non-ST segment elevation of the acute coronary syndrome and acute myocardial infarction from stable CAD." (PMID 34422136, 2021).